BCCIP (BRCA2 and CDKN1A interacting protein)
Diseases named in the same sentence as BCCIP in open-access papers (continued):
Sharing a sentence is not in itself a finding about the gene and the disease.
medulloblastoma (1 paper, 2017). A malignant, invasive embryonal neoplasm arising from the cerebellum. "Previously, we reported that a partial and transient loss of BCCIP was sufficient to initiate medulloblastoma formation but a restoration of BCCIP level is required for the progression of medulloblastoma in mice." (PMID 29047390, 2017). "In the case of medulloblastoma that developed in BCCIP-deficient mice, the tumors arose from cells in which the shBCCIP-expressing cassette had been deleted and BCCIP expression restored." (PMID 29047390, 2017). "A partial and transient loss of BCCIP was sufficient to cause medulloblastoma in mice." (PMID 29047390, 2017). "As a matter of fact, we showed previously that GFAP-Cre-mediated 50–70% downregulation of BCCIP in mouse brain was sufficient to trigger medulloblastoma." (PMID 29047390, 2017). "This is consistent with a previous report suggesting that a partial and transient reduction of BCCIP is not only sufficient but also requisite for medulloblastoma formation, likely due to its concurrent roles in the maintenance of genomic integrity and supporting cell proliferation." (PMID 29047390, 2017).
Obesity (1 paper, 2025). Accumulation of substantial excess body fat. "Further, we investigated in more detail selected DMRs in TSC22D1, HAS2, GCC1, NCKIPSD from SAT, all being hypermethylated in individuals with obesity and BCCIP, IL1R1 (hypermethylated in lean) and FMNL2 (hypermethylated in individuals with obesity) from OVAT." (PMID 41225618, 2025).
prostate carcinoma (1 paper, 2007). A carcinoma that arises from epithelial cells of the prostate gland. "Intriguingly, two genes (BCCIP, HMG20B) appeared in our analysis that interact with BRCA2, another, albeit weaker candidate for a hereditary prostate cancer gene." (PMID 17280610, 2007). "The analysis of individual genes by quantitative real-time PCR revealed that many (e.g. MX1, EPB41L3), but not all (notably BCCIP and TLR3) of the genes significant in the interaction analysis were also overexpressed generally in prostate cancers compared to benign tissues." (PMID 17280610, 2007).
skin cancer (1 paper, 2017).
squamous carcinoma (1 paper, 2023). "However, BCCIP was previously identified in EVs from A431 squamous carcinoma cells." (PMID 37981907, 2023).
triple-negative breast carcinoma (1 paper, 2017). An invasive breast carcinoma which is negative for expression of estrogen receptor (ER), progesterone receptor (PR), and human epidermal growth factor receptor 2 (HER2). "We found that the BCCIP protein level is downregulated in 49% of triple-negative breast cancer and 25% of nontriple-negative breast cancer." (PMID 29047390, 2017). "Interestingly, 49% of triple-negative breast cancer (TNBC) shows BCCIP downregulation, but only 25% of non-TNBC is BCCIP low or negative (p = 3.86 × 10–7, χ2 test)." (PMID 29047390, 2017).
tumor (14 papers, 2009 to 2025). "BCCIP is an important BRCA2 cofactor in tumor suppression, which has been implicated in many cellular processes; including telomere maintenance, recombination and damage repair, embryonic development and genomic stability." (PMID 32973865, 2020). "As an important cofactor for BRCA2 in tumor suppression, BCCIP has been implicated in many important cellular processes with obvious links to cancer." (PMID 27535137, 2016). "If the copy numbers of two independent BCCIP exons are less than the 99% confidence line of the normal DNA, a "BCCIP loss" was scored for this case of tumor." (PMID 19653894, 2009). "This tumor development is so quick and penetrant that it may precede and completely mask tumor development driven by BCCIP deficiency, which is likely a slower and longer process." (PMID 29047390, 2017). "The expression of BCCIP, a gene suggested to suppress tumor initiation but required for tumor progression, was reduced by 2-fold upon DLL1 downregulation." (PMID 31107884, 2019). "Our study supports the notion that BCCIP is a unique caretaker suppressor of tumor initiation but a requisite for tumor progression, and BCCIP dysfunction has important roles in modulating mammary tumorigenesis." (PMID 29047390, 2017). "This reinforces the concept that BCCIP serves as a unique type of tumor suppressor previously called SIRP: a suppressor of initiation but a requisite for progression." (PMID 29047390, 2017). "Compared with the de-novo tumors developed from the control mice, a reduced BCCIP protein level was found in epithelial tumor cells evolved from the benign nodules of BCCIP-CKD females." (PMID 29047390, 2017). "We found that BCCIP protein is expressed in the normal mammary epithelium, and some tumor tissues display strong BCCIP staining." (PMID 29047390, 2017). "The remaining gene with an inverse relation of expression, (227896_at) BCCIP, is involved in cell cycle regulation and it was recently shown that it promotes tumor progression." (PMID 25753926, 2015). "This suggests that loss of 53BP1 expression may be an accompanying molecular change and may be required for the BCCIP-deficient benign lesions to evolve into malignant tumors, which would resemble the relationship between BRCA1 and 53BP1 in tumor development." (PMID 29047390, 2017). "BCCIP downregulation alone in the mouse mammary gland is sufficient to trigger the formation of benign mammary nodules but these benign lesions can hardly progress into malignant stages, supporting BCCIP as a suppressor for tumor initiation but a requisite for tumor progression." (PMID 29047390, 2017). "Because of these critical functions of BCCIP in cell growth and division, it is understandable that a complete or severe loss of BCCIP may be detrimental for cell proliferation and thus BCCIP becomes a requisite for tumor progression." (PMID 29047390, 2017). "The next question is why BCCIP defect may hinder tumor progression and recovery of BCCIP function is a requisite for tumor progression." (PMID 29047390, 2017). "BCCIP suppresses the growth of certain tumor cells, but is required for tumor progression." (PMID 26965049, 2016). "The overexpression of one of BCCIP isoforms can inhibit tumor growth." (PMID 19161603, 2009). "However, downregulation of BCCIP in these mice did not synergistically promote tumor-associated death." (PMID 29047390, 2017). "BCCIP (BRCA2‐and cdkn1a‐interacting protein) serves as a critical cofactor for BRCA2 in tumor suppression." (PMID 39932052, 2025). "BCCIP binds to the protein LYRIC/AEG-1, which promotes tumor cell migration and invasion through activation of NF-kappaB." (PMID 32867128, 2020). "The BCCIP (BRCA2- and CDKN1A-interacting protein) is an important cofactor for BRCA2 in tumor suppression." (PMID 27535137, 2016).
tumor (continued). "Then, we stained serial sections of the tumor tissue arrays with anti-GFAP and anti-BCCIP antibodies." (PMID 19653894, 2009). "Then, the relative dosage of BCCIP gene in tumor DNA was compared with the distribution of normal DNA." (PMID 19653894, 2009). "Thus, it is likely that lack of BCCIP expression needs to be coupled with additional genetic alterations for tumor cells to be viable and remain aggressive." (PMID 19653894, 2009). "Although certain features, such as viable mice with no tumor formation, are common to conditional deletion of BRCA2 or BCCIP knockdown in neural cells, some features of the BCCIP-CKD mice are distinguishable from the BRCA2 knockout mice." (PMID 22292003, 2012).
cancer (12 papers, 2007 to 2023). A tumor composed of atypical neoplastic, often pleomorphic cells that invade other tissues. "Interestingly, we found that all three malignant tumors evolved from benign lesions had lost the expression of 53BP1 protein, and this association between 53BP1 negativity and BCCIP downregulation was also found in human TNBC." (PMID 29047390, 2017). "Remarkably, loss of 53BP1 staining was found in all three cases of malignant tumor evolved from the benign nodules of the CKD mice, while all three tumors with normal BCCIP tested showed normal 53BP1 expression." (PMID 29047390, 2017). "However, in relation to cancer pathology and prognostication, there is precedence for the relevance of BCCIP or CHID1." (PMID 37981907, 2023). "Abnormal regulation of BCCIP has been discovered in different cancers." (PMID 37090117, 2023). "In addition, the malignant tumors evolved from the benign nodules of BCCIP-CKD mice displayed areas of squamous differentiation within the glandular tissue, while the de-novo tumors from the BCCIP-CON mice showed few of these features." (PMID 29047390, 2017). "The role of BCCIP in other cancer types warrants additional investigations." (PMID 19653894, 2009). "Because BCCIP deficiency would impair homologous recombination (HR) and hinder cell proliferation, it was unknown how some of the benign nodules (although a relatively rare event at a frequency of 3/32) evolved into malignant tumor while BCCIP remained downregulated." (PMID 29047390, 2017). "Among these APAs, 5 APAs (INTS4, SLC27A3, BCCIP, PLK3, HR) were differentially expressed in CRC tissues, when compared with para-cancer tissues." (PMID 35487956, 2022). "Interestingly, several membrane receptors with central roles in cancer biology showed significantly better recoveries (p < 0.01, ≥2-fold) using our water-based method compared to xylene-based protocols (e.g., TOMM5/7, RAB18, BCCIP)." (PMID 35457260, 2022). "Reduced or absence of BCCIP expression have been reported in human cancers." (PMID 21966279, 2011).
BCCIP also shares sentences with these, for which no sentence is quoted: renal cell carcinoma (4 papers); hepatocellular carcinoma (3); lung carcinoma (2); brain cancer (1); breast tumors (1); gastric cancer (1); genetic disorder (1); Insulin resistance (1); oligodendroglioma (1); Skin ulcer (1).